IL27 (interleukin 27)
Diseases named in the same sentence as IL27 in open-access papers (continued):
Sharing a sentence is not in itself a finding about the gene and the disease.
influenza (continued). "They treated WT mice with recombinant IL-27 (rIL-27) following lethal dose influenza infection and found lower IL-17 levels and higher IL-10 levels correlated with increased protection without compromising viral clearance." (PMID 32974217, 2020). "Influenza models would provide a convenient avenue to investigate the role that IL-27 plays in human models of influenza vaccination." (PMID 32509600, 2020). "In influenza infection, IL‐27 augmented NK cells anti‐virus responses and IFN‐γ secretion via the NKG2D receptor." (PMID 32761753, 2020). "In a murine model of post-influenza secondary pneumococcal pneumonia the neutralization of IL-27 using an anti-IL-27 antibody was protective." (PMID 32425944, 2020). "Complementary studies in mice and humans are needed to fully understand the impact of IL-27 on the host response to influenza infection." (PMID 32974217, 2020). "Cells from both BAL and lung tissues were stained define Ly6G+ cells myeloid population as the predominant producer of IL-27 during this early period of influenza infection." (PMID 30899058, 2019). "In summary, our findings demonstrate the crucial role played by IL-27 during the early phase of influenza infection." (PMID 30899058, 2019). "Ebi3−/− mice displayed reduced IFN-γ production at the transcriptional level, suggesting IL-27 regulates NK cells responses at an early phase of influenza infection." (PMID 30899058, 2019). "Our data for the first time establishes a novel role for IL-27 in regulating early-phase effector functions of NK cells during influenza infection." (PMID 30899058, 2019). "Our data show during influenza infection myeloid cell-derived IL-27 regulates the early-phase effector functions of NK cells in the bronchioalveolar and lung tissue." (PMID 30899058, 2019). "In this study, we determined the role of IL-27 signaling in regulating NK cells effector responses during influenza infection as well as dissecting molecular mechanism of its action." (PMID 30899058, 2019). "Our study strongly suggests that IL-27 plays a crucial role during the early phase of influenza infection (DPI 1–4)." (PMID 30899058, 2019). "This suggests a unique role of IL-27 in augmenting NK cells responses during the early phase (DPI 0–4) of influenza infection." (PMID 30899058, 2019). "Collectively these data suggest IL-27 plays a primary role in the production of IFN-γ from NK cells during the early phase of influenza infection in vivo." (PMID 30899058, 2019). "Collectively, these findings provide a novel insight into the stimulatory functions of IL-27 on NK cells in the trachea and alveolar space of the lungs during influenza infections." (PMID 30899058, 2019). "Whereas IL-27 does not impact immune control of murine parainfluenza Sendai virus (SeV) infection, early IL-27 can impair control of influenza infection." (PMID 30044874, 2018). "We demonstrate that early influenza infection significantly reduced levels of pneumococcus driven IL-12p70, IL-23 and IL-27 in human monocytes with significant impairment of IL-17A and IFN-γ in HKSP-treated allogeneic mixed lymphocyte cultures." (PMID 30192848, 2018). "Recent studies have shown that IL-27 can inhibit replication of viruses, such as influenza, hepatitis C, and HIV-1." (PMID 28452924, 2017). "First, we show that IL-27 mRNA levels increase during influenza infection, peaking at day 6 post-infection and returning to baseline by day 12 post-infection." (PMID 25651926, 2015). "In influenza, application of IL-27 in a late phase of infection improved survival by reducing immunopathology and monocyte / neutrophil infiltration into the lung." (PMID 26360023, 2015). "To further investigate the role of IL-27 in bacterial host defense, we examined lung inflammation in our influenza, S. aureus co-infection model." (PMID 25651926, 2015). "IL-27 has also been shown to cooperate with IL-2 from CD4+ helper T cells to induce IL-10 through a Blimp-1 dependent mechanism during influenza infection." (PMID 25651926, 2015).
influenza (continued). "In our current study, we observed increased IFNγ protein levels in the influenza-infected IL-27Rα−/− mice compared to WT, confirming that IL-27 signaling attenuates IFNγ production during influenza infection." (PMID 25651926, 2015). "Our findings demonstrate that lack of IL-27 signaling results in improved clearance of S. aureus during influenza, S. aureus co-infection." (PMID 25651926, 2015). "All these data suggest that influenza infection up-regulated IL-27 production in an IFNAR-dependent manner." (PMID 24408967, 2014). "Our study in a mouse model of influenza shows that the cytokine IL-27 plays a crucial role in survival by protecting against lung damage." (PMID 24809349, 2014). "This suggests that interference with leukocyte recruitment in the early phase of influenza aggravates the infection, and the low level of endogenously produced IL-27 in this early phase is appropriate to allow their unhindered rapid activity in virus defense." (PMID 24809349, 2014). "We now report that influenza infection induced pulmonary IL-27 production in a type I IFN-α/β receptor (IFNAR) signalling-dependent manner, which sensitized mice to secondary pneumococcal infection downstream of IFNAR pathway." (PMID 24408967, 2014). "To assess the impact of IL-27 on survival during influenza, we challenged wild-type (WT) C57BL/6 or IL-27 receptor-deficient (Il-27ra−/−) mice with 3000 egg infectious dose (EID) influenza virus." (PMID 24809349, 2014). "In conclusion, our study shows that endogenous IL-27 has a crucial role in preventing a fatal disease course in influenza where it acts to limit and resolve the inflammatory process while allowing an unimpaired antiviral response." (PMID 24809349, 2014). "Following S. pneumoniae challenge on day 5 after primary influenza infection, we also found that secondary infected mice had a synergistic increase in IL-27 production compared with mice infected with either S. pneumoniae or influenza virus alone." (PMID 24408967, 2014). "Taken together, these data demonstrate that endogenous IL-27 limits the magnitude of effector cytokine production by T cells during influenza." (PMID 24809349, 2014). "Our data point to a mechanism by which IL-27 has a deleterious effect on the clearance and survival following secondary pneumococcal infection after influenza infection." (PMID 24408967, 2014). "Ongoing studies should continue to identify additional suppressive functions of IL-27 over time depending on the progress of secondary pneumococcal pneumonia after influenza infection." (PMID 24408967, 2014). "Our findings suggest that IL-27 is a potential candidate for the treatment of immunopathology, as endogenous IL-27 was found to play a major role in dampening of exaggerated inflammation in influenza while having little impact on virus elimination." (PMID 24809349, 2014). "IL-27 induces IL-10+ secretion by IFNγ+virus-specific T cells (Tr1-like cells), controlling exacerbated inflammation and conferring host protection from immunopathology in the lung during influenza infection." (PMID 38966644, 2024). "Moreover, HepG2 cells infected with avian and human influenza upregulate MX1 to a greater extent following IL-27 treatment, and this was unaffected by the presence of IFNα and IFNγ neutralizing antibodies." (PMID 35634328, 2022). "However, other studies have shown that IL-27 limits migration of neutrophils from the BM to the site of inflammation by reducing production of cytokines and chemokines during influenza infection and septic peritonitis." (PMID 26991425, 2016). "Our findings demonstrate that IL-27 may partially regulate IL-17 and IL-10 production during influenza infection." (PMID 25651926, 2015). "Since IL-27 has been shown to inhibit Type 17 responses, we further explored the contribution of IL-27 in a mouse model of influenza infection, S. aureus pneumonia, and influenza and S. aureus co-infection." (PMID 25651926, 2015).
influenza (continued). "Importantly, co-infected IL-27Rα−/− mice have increased production of IL-17 F and IL-22 compared to co-infected WT mice, suggesting that IL-27 signaling significantly impacts Type 17 immunity during influenza, S. aureus co-infection." (PMID 25651926, 2015). "It is important to note that IL-27 mediated IL-10 and IL-17 production may be variable throughout the time course of post-influenza S. aureus pneumonia and further study is required." (PMID 25651926, 2015). "The results extend our previous findings in an influenza infection model and suggest that application of IL-27 might represent an interesting therapeutic option to control leukocyte-mediated immunopathology in infectious or sterile inflammatory diseases." (PMID 26360023, 2015). "Because IL-10 production was severely decreased in influenza infected IL-27Rα−/− mice compared to controls, we proposed that IL-27 induction of IL-10 might play a role in the development of secondary S. aureus pneumonia." (PMID 25651926, 2015). "In addition to mediating IL-17 and IL-10 responses, it has been reported that IL-27 signaling affects IFNγ production by CD8+ cells during primary influenza infection." (PMID 25651926, 2015). "IL-27 mediated suppression of IL-17 may represent an important pathway limiting influenza induced inflammation." (PMID 25651926, 2015). "As leukocyte trafficking is controlled by adhesion molecules and chemokines presented on endothelial cells, we tested whether IL-27 affects key molecules involved in the recruitment or retention of innate leukocytes in influenza." (PMID 24809349, 2014). "Influenza infection could also potently induce IL-27 production in human monocyte-derived DC, monocytes, pulmonary epithelial cells and lymphocytes, while HkSp further enhanced the effects of influenza virus on IL-27 secretion." (PMID 24408967, 2014). "In summary, influenza infection induced IL-27 production in an IFNAR-dependent pathway, which suppressed innate IL-17A production by γδ T cells upon secondary pneumococcal infection in a STAT1-dependent manner, thereby promoting the development of secondary pneumococcal pneumonia." (PMID 24408967, 2014). "Thus, IL-10 becomes induced in IFN-γ+CD4+ T cells during influenza by IL-27, in part mediated via STAT4." (PMID 24809349, 2014). "In this study, we have developed a murine model of postinfluenza pneumococcal pneumonia using mice defective for IL-27 receptor signalling (IL-27R−/− mice) to investigate the effects of IL-27 induced during influenza infection on host immunity to pneumococcal infection." (PMID 24408967, 2014). "The results suggest that IL-27 dampens IFN-γ-production by T cells during influenza." (PMID 24809349, 2014). "Using influenza as a model, live attenuated and killed inactivated influenza vaccines stimulate many shared pathways such as signaling of many interleukins (including IL-1, IL-4, IL-6, IL-13, IL-20, and IL-27), interferon signaling, MARK1 activation, and neutrophil degranulation." (PMID 33777032, 2021). "Thus, IL-27 plays an essential role in the early NK cell-mediated functions as well as regulates adaptive immune response determining the pathophysiological outcome of influenza infection." (PMID 30899058, 2019). "The fact that IL-27 neutralization or IL-17A administration could restore anti-pneumococcal effects opens a new door for protecting human population from secondary pneumococcal infections especially during influenza pandemics." (PMID 24408967, 2014). "However, the role of IL-27 in the pathogenesis of secondary pneumococcal pneumonia after influenza is unknown." (PMID 24408967, 2014).
influenza (continued). "Although multiple studies have addressed the basis for the inhibitory effects of IL-27 on Th1, Th2 and Th17 cell responses, this is the first study linking IL-27 to IL-17A suppression in innate γδ T cells, which sensitized the host to secondary pneumococcal pneumonia following influenza infection." (PMID 24408967, 2014). "We therefore investigated the impact of IL-27 and its receptor IL-27Rα on immunopathology using the highly mouse pathogenic strain A/PR/8 (H1N1) and subsequently explored the therapeutic potential of recombinant IL-27 (rIL-27) to treat inflammatory lung disease in influenza." (PMID 24809349, 2014). "Rapanea melanophloeos has been shown to increase IL-27 production, ultimately increasing IL-10 production, to decrease the viral titre of influenza A virus in MDCK cells, suggesting its role as an anti-influenza treatment." (PMID 38674902, 2024). "CD8+ T cells produce IL-10 in response to IFNAR signaling, IL-27, and CD4+ T cell-derived IL-2 during influenza infection in mice." (PMID 32974217, 2020). "A recent report has demonstrated that IL-27 promotes murine NK cell cytotoxicity and IFN-g production in an NKG2D-dependent manner during influenza infection." (PMID 32509600, 2020). "IL-27 induces IL-10 expression by CD8+ T cells, and IL-27-dependent control of influenza-induced inflammation is partially dependent upon IL-10." (PMID 27926930, 2016). "Firstly, we found that IL-27 levels in the bronchoalveolar lavage (BAL) and serum samples from influenza-infected patients were significantly elevated compared with control individuals." (PMID 24408967, 2014). "Therefore IL-27 seems to have a critical function in NK cell-mediated functions through transcriptional pathways regulated by Mafs and Nrf2 and may play a role in the regulation of adaptive immune response that can determine the pathophysiological outcome after infection by influenza." (PMID 32722164, 2020). "Remarkably, IL-27 production was significantly reduced in IFNAR-deficient BMDC, monocytes, LEC and lymphocytes after influenza infection with or without HkSp co-stimulation compared with WT cells." (PMID 24408967, 2014). "However, there was little impact of IL-27 signaling on host defense against S. aureus in the absence of preceding influenza." (PMID 25651926, 2015). "In addition, in the absence of IL-27 signaling, IL-10 production during influenza infection is attenuated." (PMID 25651926, 2015). "The role of IL-27 in influenza has not been comprehensively studied." (PMID 24809349, 2014). "Our data show that after influenza infection CD27+CD11b+ effector NK cells appear in the alveolar space and lung tissue of WT mice but not in Il27ra−/− mice, suggesting a critical role for IL-27 in regulating this NK subset." (PMID 30899058, 2019). "Lack of IL-27Rα (Wsx1) or IL-27 subunit EBI3 resulted in impaired NK cell-mediated effector functions and ineffective clearance of influenza infection." (PMID 30899058, 2019). "Although the role of IL-27 in driving CD8+ T cell responses in infectious disease is less studied, initial studies showed that in the absence of IL-27Ra, CD8+ T cell responses are not effective during infection with Trypanosoma cruzi and influenza." (PMID 34996392, 2022).
prostate carcinoma (26 papers, 2014 to 2025). A carcinoma that arises from epithelial cells of the prostate gland. "After excluding these potential pleiotropic SNPs, the associations between IL-6, IL-27 and prostate cancer risk remained consistent in the sensitivity analyses." (PMID 36733309, 2023). "IL-30 (IL-27 p28 form) expression from prostate cancer cells is associated with advanced-grade prostate cancer and IL-30 stimulates prostate cancer cell proliferation in vitro." (PMID 30158439, 2018). "In this manuscript, we describe the therapeutic administration of IL-27 in a sequential manner with IL-18 for treating prostate cancer." (PMID 34209203, 2021). "IL-27 has shown promise in halting tumor growth and mediating tumor regression in several cancer models, including prostate cancer." (PMID 34209203, 2021). "We describe our findings on the effects of IL-27 gene delivery on prostate cancer cells and how sequential therapy with IL-18 enhanced the efficacy of IL-27." (PMID 34209203, 2021). "In this in vitro setting, we detected significant reduction in TC2R prostate cancer cell viability when IL-27 was used alone or co-administered with IL-18 relative to untreated control (*, p < 0.05) and each single cytokine alone (#, p < 0.05)." (PMID 34209203, 2021). "It is worth noting that IL-27R expression (i.e., an indicator of IL-27 responsiveness) is lost in high-grade and advanced-stage prostate cancer cells." (PMID 34045653, 2021). "Interleukin-27 (IL-27) can partially reduce tumor growth in several animal models, including prostate cancer." (PMID 34209203, 2021). "Interleukin-27 (IL-27) has shown promise in halting tumor growth and mediating tumor regression in several models, including prostate cancer." (PMID 32046108, 2020). "The expression of IL-6 can also be driven by IL27-p28 (IL-30), which has tumor-promoting effects in prostate cancer and in breast cancer is enriched for and associated with the TNBC subtype." (PMID 32023849, 2020). "IL-27 also directly induces apoptosis in prostate cancer cells, multiple myeloma, non-small cell lung cancer, and ovarian cancer cells." (PMID 31681561, 2019). "Studies on IL-27's effects in PCa have so far been carried out both in vitro with murine prostate cancer cell lines and in vivo with immune-competent murine PCa models." (PMID 24681516, 2014). "The positive relationship between IL-6 and prostate cancer and the null finding for IL-27 might be robust as the relationship retained consistent across analyses that excluded pleiotropic SNPs." (PMID 36733309, 2023). "This has led to the investigation of IL-27 as a therapeutic for prostate cancer." (PMID 35336801, 2022). "Additionally, IL-27 exhibits immunomodulatory activity capable of promoting the accumulation of tumor-clearing effector cells at the site of prostate-cancer bone metastases." (PMID 35200430, 2022). "Similar antiproliferative properties of IL-27 were also observed in prostate cancer cells." (PMID 34045653, 2021). "Similarly, IL-27 inhibited proliferation and increased apoptosis of human prostate cancer cells, multiple myeloma (MM) primary cells and cell lines, non-small cell lung (NSCLC) cancer cells, and ovarian cancer cell lines." (PMID 28255204, 2017). "In addition, different from the IL-27 heterodimer, which inhibits prostate cancer cell proliferation and survival, IL-27p28 (IL-30) has shown a protumorigenic role in both human prostate and breast cancer." (PMID 28255204, 2017). "Our results suggest that the targeted form of IL-27 may be utilized as a strategy impacting cell translation initiation through modulating the eIF2α pathway (ER stress leading to apoptosis) as a novel approach for treating prostate cancer." (PMID 32046108, 2020). "To further validate the effects of IL27 on immune response in human cancers, we investigate whether upregulated genes in response to IL27 treatment will be positively co-expressed with IL27 in human prostate cancer (GSE32448) and melanoma cancer (the TCGA-SKCM cohort)." (PMID 34733272, 2021).
prostate carcinoma (continued). "Our results suggest that the targeted form of IL-27 may be utilized as a strategy impacting cell translation initiation through modulating the eIF2α pathway (stress to the endoplasmic reticulum (ER) leading to apoptosis) as a novel approach for treating prostate cancer." (PMID 32046108, 2020). "IL-27 also induced the expression of IDO and PD-L1 in human PC3 prostate cancer cells and in A549 lung adenocarcinoma and monocyte-enriched populations, suggesting a broader effect of IL-27." (PMID 26657115, 2015).